CRP (C-reactive protein)
Diseases named in the same sentence as CRP in open-access papers (continued):
Sharing a sentence is not in itself a finding about the gene and the disease.
diabetes (continued). "Additional significant predictors identified included advanced age, diabetes mellitus, increased left atrial diameter, elevated serum ST2, hs-CRP levels, and higher CHA2DS2-VASc scores." (PMID 40842477, 2025). "This is consistentwith previous studies showing that diabetes, LDL-C, and CRP are independentpredictors of the presence of TCFA in CHD patients." (PMID 41356323, 2025). "These include high-sensitivity C-reactive protein (hs-CRP), B-type natriuretic peptide (BNP), and serum creatinine as well as clinical indicators such as age, sex, diabetes, coronary artery disease, and congestive heart failure." (PMID 40947484, 2025). "The PAS patients were older and had higher SBP, more diabetes, and higher serum PCS and C-reactive protein (CRP) than the control group." (PMID 41008726, 2025). "The high-CRP/HDL-c quantile group exhibited greater proportions of males, individuals with diabetes and hypertension (P < 0.001)." (PMID 40655403, 2025). "Based on the findings of univariate analysis, the following parameters were entered in the multivariate logistic regression model: age, SBP, diabetes duration, FPG, 2 h-PG, HbA1c, HDL-C, CRP, HBG, CRP/HDL-C." (PMID 40104822, 2025). "In our model hs-cTnI outranked age, phosphate, diabetes mellitus, BNP, hs-CRP, and a history of previous coronary events." (PMID 40600070, 2025). "The influential factors identified through this analysis were age, gender, BMI, smoking, hypertension, diabetes, coronary artery disease, WBC, Neu, Lym, PLT, CRP, Alb, D-dimer, lactate, APACHE II score, and SOFA score." (PMID 40333671, 2025). "This study aimed to explore the relationship between the inflammation-lipid indicator C-reactive protein (CRP)/high-density lipoprotein cholesterol (HDL-C) and DR occurrence in subjects with type 2 diabetes mellitus (T2DM)." (PMID 40104822, 2025). "Similarly, the European Prospective Investigation into Cancer and Nutrition (EPIC)-Potsdam study reported that higher levels of IL-6 and CRP were associated with an increased risk of T2DM in a European cohort, reinforcing the inflammatory hypothesis of diabetes." (PMID 41523554, 2025). "This study utilised LR, RF and XGBoost models to build and validate a sarcopenia risk prediction tool for patients with stroke, incorporating seven variables: age, limb dysfunction, diabetes, tube feeding, BMI, NIHSS score and CRP." (PMID 39979762, 2025). "The present study aimed to assess the predictive value of first-trimester biochemical and clinical markers - CRP, uric acid, PPBS, BMI, history of PCOS, and family history of diabetes - for GDM in a South Indian cohort." (PMID 41200603, 2025). "In particular, elevated circulating inflammatory markers such as C-reactive protein (CRP) and interleukin-6 (IL-6) predict the development of type 2 diabetes mellitus." (PMID 39852208, 2025). "Subgroupanalyses revealed that after adjusting for age, gender, coronary heart disease,hypertension, diabetes mellitus, NYHA class IV, LVEF, lgBNP, and CRP levels, HRvalues in the first to fifth groups decreased gradually." (PMID 41209128, 2025). "CRP sensitivity and specificity (5 mg/L cut-point) was determined in reference to sputum test results and compared by country, sex, and HIV and diabetes status." (PMID 38712173, 2024). "In our study, we found that an APACHE II score ≥ 15; diabetes mellitus; and high procalcitonin, lactic dehydrogenase, BNP, CRP and plasma IL-6 levels were significant variables in the univariate analysis (p < 0.05)." (PMID 38523173, 2024). "Compared with the low NPAR group, the high NPAR group had a shorter survival time, older age, higher proportions of diabetes and cardiovascular diseases, and higher levels of inflammatory-related parameters such as WBC, CRP, CAR, and NLR (p < 0.05)." (PMID 38178381, 2024). "Values of diabetes, RDW, LVEF, CRP, and UAR exhibited a variance inflation factor < 10, a tolerance degree > 0.1, and all of them were included in the multivariate logistic regression model." (PMID 38269629, 2024).
diabetes (continued). "They identified elevated CRP levels with poor post-revascularization outcomes in patients with CLTI and diabetes." (PMID 38672153, 2024). "Cox regression analysis shows that some indexes such as caIMR, leukocyte, CRP, BNP (peak), cTnI (seventh day), LVEF, furosemide/antisterone use, diabetes, and Killips classification were important prognostic indicators of patients with STEMI." (PMID 38978390, 2024). "The recurrent group had significantly different proportions of sex, BMI, hypertension, diabetes mellitus, TOAST classification, anemia, CRP, decreased eGFR, white matter changes, and CMBs compared with the first-ever group." (PMID 39407804, 2024). "The higher WBC counts, CRP, ESR, and particularly the elevated SII and dNLR, reflect a heightened inflammatory state in patients with diabetes." (PMID 39767619, 2024). "Age, sex, smoking, BMI, LVEF, diabetes, hypertension, obesity, fasting glucose, fasting insulin, the HOMA-IR index, hs-CRP, statin use and insulin use were included in the multivariate analysis." (PMID 39590197, 2024). "As compared to premenopausal women, postmenopausal women had higher ferritin, BMI, CRP, and SBP levels, more prevalent CVD and diabetes, reported higher consumption of anti-diabetic and antihypertensive medications, and had lower transferrin levels." (PMID 38715055, 2024). "Increased levels of hs-CRP and ESR are better markers of systemic inflammation which is related to metabolic syndrome like diabetes." (PMID 39100011, 2024). "Hypertension, diabetes mellitus, APACHE II score ≥ 15, procalcitonin, CRP, IL-6 and lactate dehydrogenase had significant effects on the development of hypoactive delirium compared with the no delirium group (p < 0.05)." (PMID 38523173, 2024). "Formula NBF1, which is rich in seaweed fiber and n-3 PUFA, was found to positively affect C-reactive protein (CRP) and reduce adiponectin (APN) and diabetes-related markers." (PMID 39596859, 2024). "Individuals with diabetes had greater mean values for the FBS test (287.78 mg/dL), D-dimer (2639.2 ng/mL), and CRP (117 mg/L)." (PMID 39995847, 2024). "This study investigates the correlation between hs-CRP and HbA1c levels in patients with acute myocardial infarction (AMI) and type 2 diabetes mellitus (T2DM) and evaluates their impact on six-month mortality outcomes." (PMID 39286672, 2024). "This meta-analysis aimed to examine the influence of chia consumption on three inflammatory markers: CRP, IL-6, and TNF-α in individuals with type 2 diabetes mellitus or overweight." (PMID 39703891, 2024). "Inflammatory markers such as C-reactive protein (CRP) and interleukin-6 (IL-6) are often elevated in individuals with depression, diabetes, and prediabetes." (PMID 39457589, 2024). "Sex, smoking history, drinking history, coronary artery disease, neuropathy, PVD, retinopathy, nephropathy, BMI, duration of diabetes, TC, FBG, HDL-C, LDL-C, hs-CRP, and Ua factors were more homogeneous (I2<50%); thus, a fixed-effects model was applied." (PMID 39280008, 2024). "Hepatic steatosis had positive correlations with LSM, weight, BMI, ALT, AST, GGT, ALP, TG, hs-CRP, HbA1c, insulin, HOMA-IR, HOMA-IS, eGFR, smoking status, diabetes, and hypertension." (PMID 38721033, 2024). "Plasma angiogenin significantly correlated positively with diabetes duration, mean arterial pressure, triacylglycerol, urine ACR, high sensitivity c-reactive proteins (hs-CRP) and inversely with HDL-cholesterol and eGFR." (PMID 38360721, 2024). "Age, percentage of patients with hypertension and diabetes mellitus, median NIHSS score, CRP, median neutrophil count, MHR and NLR were higher in the FR group than in the control group." (PMID 38886670, 2024). "These saliva biomarkers, in addition to C-reactive protein (CRP), support the use of this fluid as a method to aid in the evaluation of systemic inflammation and glycemic control in diabetes patients." (PMID 39795606, 2024).
diabetes (continued). "C-reactive protein (CRP) and interleukin-6 (IL-6) have been identified as strong predictors of both diabetes and CVD in prospective cohort studies." (PMID 39408364, 2024). "In our study, we demonstrated that NSTEMI patients with poorly developed CCC were more likely to have diabetes, higher UAR values and elevated CRP levels compared to those with well‐developed CCC." (PMID 38269629, 2024). "Age, low education, current smoker, BMI, hypertension, diabetes mellitus, ischemic heart disease, chronic kidney disease, stroke, and ECG abnormalities were significantly higher with higher serum hs-CRP levels." (PMID 38548879, 2024). "Patients with high CAR showed an older age and a higher incidence of diabetes and had higher levels of LDL, white blood cell count, neutrophil count, CRP level in contrast as well as lower HDL cholesterol and albumin levels." (PMID 38673005, 2024). "The shared characteristics between RSP and PRISm were dyspnea, chronic bronchitis, rheumatic disease, diabetes, IHD, increased BMI, fasting glucose, and CRP but also CT findings such as BWT, ILA, and bronchiectasis." (PMID 39079106, 2024). "The distinguishing factors were age, sex, comorbidities (including diabetes and tumor), and levels of AST, AST/ALT ratio, C-reactive protein, hemoglobin, albumin, and prealbumin." (PMID 39555696, 2024). "The deceased patients were observed to be mostly older males with an increased prevalence of diabetes and tumors, signifying higher AST and C-reactive protein levels." (PMID 39555696, 2024). "Inflammation markers, including C-reactive protein (CRP), interleukin 6 (IL6), E-selectin, and soluble intercellular adhesion molecule 1 (sICAM-1), exert a function in diabetes development." (PMID 39339769, 2024). "The associated increased risk of the recurrent group was particularly high in patients with male sex, high BMI, hypertension, diabetes mellitus, TOAST classification, anemia, leukocytosis, CRP, decreased eGFR, white matter changes, and CMBs." (PMID 39407804, 2024). "CRP is a common inflammatory biomarker in chronic diseases like CKD, diabetes, and cardiovascular diseases." (PMID 38671065, 2024). "CRP, C-reactive protein; Hb, hemoglobin; HDL-C, high-density lipoprotein cholesterol; LDL-C, low-density lipoprotein cholesterol; T2DM, type 2 diabetes mellitus." (PMID 38333459, 2024). "The group experiencing all-cause death was characterized by older age, a higher prevalence of diabetes, hypertension, stroke, and CKD, increased usage of hypotensive and hypoglycemic drugs, elevated SBP, Lp(a), uric acid, HbA1c, FIB, Hs-CRP, and GRACE scores." (PMID 38812817, 2024). "Diabetes mellitus, fatty liver, high white blood cell count (WBC), C-reactive protein (CRP), red blood cell distribution width (RDW), procalcitonin (PCT), SII, NLR, NPR, CAR, CLR, and TyG index, and a low LMR were significantly associated with SAP." (PMID 38317108, 2024). "Subgroup analyses demonstrated that the association between CRP levels and all-cause mortality remained significant across subgroups of age (≤ 60 and > 60 years), gender (male), presence or absence of hypertension, non-diabetes, cardiovascular disease, non-cardiovascular disease and non-cancer." (PMID 38858782, 2024). "Yet, C-reactive protein failed to contribute significantly to the association between triglycerides and diabetes in this study, suggesting that inflammation might not play a significant role in high-triglyceride-induced diabetes." (PMID 38611646, 2024). "We confirmed that the correlation between DLR and hospital death and ICU death was nonlinear after adjusting age, male, BMI, smoking, hypertension, diabetes, WBC, Neu, PLT, CRP, Alb, creatinine, BUN, uric acid, lactate, APACHE II score, and SOFA score." (PMID 39877653, 2024). "A nomogram was constructed based on age, KPS, BMI, diabetes status, targeted therapy, Hb, WBC, LDH, CRP, PLR, and LMR." (PMID 39635526, 2024).
diabetes (continued). "Age, proportion of patients with hypertension and diabetes mellitus, median NIHSS score, CRP level, procedure duration time, neutrophil count and NLR were higher in the FR group than in the control group." (PMID 38886670, 2024). "Independent predictors of ICU admission were age, CRP, LDH and diabetes as well as corticosteroid use prior to admission." (PMID 38750134, 2024). "As shown inTable 1: age, diabetes, hypertension, APACHE II, SAPS II, heart rate, MAP, serum baseline urea and creatinine, WBC count, CRP, shock, MV and nephrotoxic antibiotics were all predictors of AKI in univariate analysis." (PMID 39839732, 2024). "Compared with the alive patients, those died were older, higher proportion of males, more patients had diabetes, tumor as well as higher levels of AST, AST/ALT ratio and C-Reactive protein." (PMID 39555696, 2024). "In men, only age (<0.0001), the presence of elevated CRP levels (<0.0001), HDL cholesterol (P = 0.03), diabetes (P = 0.02), and BMI retained a statistically significant association with CV events after correction for the other variables." (PMID 39196799, 2024). "Risk factors for sepsis in multivariable analysis were a history of diabetes mellitus (DM) (OR = 4.24, p = 0.007), shock index (SI) (×10−1) (OR = 1.55, p < 0.001), C-reactive protein (CRP) (mg/dL) (OR = 1.08, p = 0.005), and neutrophil to lymphocyte ratio (NLR) (×10) (OR = 1.58, p = 0.007)." (PMID 39064542, 2024). "Inflammatory markers CRP and ESR were significantly elevated in the patients with diabetes (CRP: 78.5 ± 20.7 mg/L vs. 60.3 ± 18.5 mg/L, p < 0.001; ESR: 52.7 ± 15.3 mm/h vs. 40.8 ± 12.9 mm/h, p < 0.001), suggesting a heightened systemic inflammatory response." (PMID 39767619, 2024). "In terms of inflammation pathways, chronic inflammation markers such as high-sensitivity CRP, IL-6, and TNF-α have been shown to be elevated prior to the onset of diabetes." (PMID 38188453, 2024). "After adjusting for some clinical, biochemical, and inflammatory parameters (such as age, sex, hypertension, diabetes and cardiovascular disease, Hb, PLT, SCR, phosphorus, LDL, CRP), the result remained statistically significant (SHR = 2.30, p = 0.002)." (PMID 38178381, 2024). "Statistically significant variations were observed among the SII quartiles with respect to age, sex, race, smoking, hypertension, diabetes, HDL, LDL, total cholesterol, waist circumference, high-sensitivity CRP, and BMI (p < 0.05)." (PMID 39116149, 2024). "A multivariable regression model including LAP index, age, ALT, uric acid, HbA1c, CRP, total cholesterol, LDL, BMI, and diabetes duration explained almost 62% of mitral E/A variation (adjusted R2 for the model: 0.619, p = 0.000)." (PMID 38836221, 2024). "Above results had demonstrated a positive association (p < 0.05) between mortality and variables containing age, sex, CKD etiology, diabetes, tumor, AST, AST/ALT ratio, C-Reactive protein, hemoglobin, albumin, prealbumin, inhalation drugs, and vaccination." (PMID 39555696, 2024). "Consecutive outpatient adults with cough ≥2 weeks from five TB endemic countries in Africa and Asia had baseline blood collected for point-of-care CRP testing and HIV and diabetes screening." (PMID 38712173, 2024). "As the RMS increased, there was a concurrent decrease in the incidence of CVD, hypertension, dyslipidemia, diabetes, and SBP, as well as in TG and CRP levels; meanwhile, grip strength and HDL-C increased." (PMID 39026227, 2024). "In univariate analysis, caIMR, leukocyte, CRP, BNP (peak), cTnI (seventh day), LVEF, furosemide/antisterone use, diabetes, Killips classification, and post–PCI TIMI were important predictors of prognosis in patients with STEMI." (PMID 38978390, 2024). "Age, sex, ethnicity, smoking status, household income, educational attainment, BMI as well as diabetes, hypertension, TC, LDL-C, ALT, AST, GGT, Alb, HbA1c, CRP, and ferritin levels were significant factors in all TG/HDL-C quartiles (P < 0.05)." (PMID 39081791, 2024).
diabetes (continued). "DNA: deep neck abscess; NSTI: necrotizing soft tissue infection; CRP: C-reactive protein; WBC: white blood cell; DM: Diabetes mellitus; Winter: Winter’s classification; PG: Pell and Gregory classification." (PMID 39493048, 2024). "The influential factors included age, male, BMI, smoking, hypertension, diabetes, WBC, Neu, PLT, CRP, Alb, creatinine, BUN, uric acid, lactate, APACHE II score, and SOFA score." (PMID 39877653, 2024). "Unadjusted logistic regression analysis revealed that age, diabetes, lymphocyte count, total albumin, the SII and the CRP level were correlated with POD." (PMID 38566241, 2024). "The between-group differences in age, diabetes mellitus status, CVD status, BMI, Hb, ALB, hs-CRP, NLR, TG, prealbumin and 4-h D/Pcr were statistically significant (all P < 0.05)." (PMID 38918730, 2024). "Model 3 adjusted for education level, body mass index, smoking, alcohol consumption, diabetes, hypertension, HDL-C, triglyceride and Hs-CRP on the basis of model." (PMID 38914954, 2024). "In our population, those patients with diabetes and stress hyperglycemia had significantly higher levels of NLR, serum concentrations of C-reactive protein, D-dimer, and ultra-high sensitivity troponin-l compared to the group without diabetes." (PMID 39079143, 2024). "Other variables included in the multivariate analysis were hypertension, diabetes mellitus, chronic kidney disease, embolism, NYHA III/IV, S. aureus infection, age, C-reactive protein, hemoglobin, creatinine, and platelet count." (PMID 38251219, 2024). "Participants eating pro-inflammatory and pro-oxidative diets were more likely to be Hispanic white and female and had higher cotinine, BMI, CRP, RDW, prevalent CVD, hypertension and diabetes." (PMID 37513566, 2023). "In women, these variables were age, WC, BMI, TC, LDL-cholesterol, AST, ALT, CRP, SBP, DBP, presence of hypertension, and presence of diabetes." (PMID 37409278, 2023). "Specifically, previous PCI, diabetes mellitus, and postprocedure residual stenosis resulted as independent predictors of early ISR, while previous PCI and C-reactive protein (CRP) levels were correlates of late ISR." (PMID 36769886, 2023). "A multivariate logistic regression was conducted including age, BMI, hypertension, diabetes, smoking history, adjuvant chemotherapy and anti-HER2 therapy, ferritin levels, hs-CRP levels, and CD3 + T cells." (PMID 37308936, 2023). "In conclusion, we have reported evidence for the detrimental effect of both wealth and CRP for predicting future CHD, stroke and diabetes/high blood glucose, and cardiometabolic multimorbidity." (PMID 37808231, 2023). "It is a simple utility that CRP or lipid variables reflect the body, while β-blockers, CVD history, and diabetes are closely related to the patient’s past history and fail to highlight the characteristics of hemodialysis." (PMID 37171338, 2023). "CRP: c-reactive protein; IL6: interleukin 6; MDA: malondialdehyde; SUA: serum uric acid; T2DM: type 2 diabetes mellitus; TAC: total antioxidant capacity; TNF-α: tumor necrosis factor-alpha." (PMID 38034261, 2023). "Age, BMI, WBC counts, NLR, CRP, cortisol, DHEAS, CDR, and proportion of participants with hypertension, diabetes mellitus, and dyslipidemia differed between men, premenopausal and postmenopausal women." (PMID 37373720, 2023). "Among participants with diabetes, males had higher levels of blood glucose, HOMA-IR and TC, while females had higher levels of CRP, TC and LDL-C." (PMID 37264434, 2023). "The participants in different CVAI quartiles differed in age, gender, family history of CAS, education status, marital status, smoking, drinking, diet, shifts status, hypertension, diabetes, dyslipidemia, BMI, WC, TG, FPG, SBP, DBP, UA, Hcy, hs-CRP, and WBC." (PMID 36839381, 2023). "We adjusted for variables including age, sex, CRP, HGB, LDL-c, HDL-c, TG, FPG, HCT, HBA1c, hypertension, diabetes SBP, CKD, CHD, mental illness, CLD, drinking status, and smoking status." (PMID 37484946, 2023).